CXCL9 (C-X-C motif chemokine ligand 9)
Diseases named in the same sentence as CXCL9 in open-access papers (continued):
Sharing a sentence is not in itself a finding about the gene and the disease.
tumor (continued). "This may also explain why peripheral (systemic) administration of CXCL9-Fc or CXCL10-Fc limits tumor growth even though systemic administration of these agents would be expected to compromise the chemokine gradients that allow the endogenous CXCR3 ligands to attract T cells into the tumors." (PMID 39474427, 2024). "However, a notable increase was observed in the tumor cell‐intrinsic expression of Cxcl9/10." (PMID 39316363, 2024). "Moreover, inhibition of COX2 by aspirin could also recruit natural killer cells and cytotoxic T lymphocytes into tumor microenvironment via increasing the secretion of CXCL9 and CXCL10." (PMID 37973900, 2023). "Among 28 chemokine genes available, CXCL9/10/11/CXCR3, CXCL13/CXCR5 and XCL1/XCR1 mRNA expression were significantly increased in RCC compared to normal kidney tissue and also strongly associated with tumor-infiltrating effector memory and central memory CD8+ T cells in all investigated collectives." (PMID 37006314, 2023). "Those inflamed tumor subtypes are characterized by anti-tumor immune cell infiltration, more potent activation of interferon signaling, higher level of chemokine secreting such as CXCL9/10, and less immune-suppressive stroma including CAFs, abnormal tumor endothelium, etc." (PMID 37658364, 2023). "Therefore, more investigations on CXCL9 in the tumor microenvironment are required to learn whether it has any clinical relevance for immunotherapy or could serve as a predictive biomarker for UCEC." (PMID 36845675, 2023). "Moreover, specific co-expression of CXCL9 and αPD-L1 in various tumor cells is achieved by replacing the tyrosinase promoter of NPTyr-C9AP with a survivin promoter, which increases T-cell infiltration and activation and therapeutic efficacy in multiple tumors in female mice." (PMID 37031188, 2023). "PGE2 can also act on human type 1 conventional dendritic cells (DCs) leading to anti-tumor dysfunction by downregulating their expression of T cell recruiting chemokine ligands such as CXCL9 and CXCL10 and production of IL-12 which could also impair NK cell function." (PMID 38022679, 2023). "Thus, the CXCL9/10/11-CXCR3 axis promotes the recruitment of anti-tumor T cells into the tumor." (PMID 36531014, 2022). "Interestingly it appears that the main source of CXCL9 is macrophages in multiple tumor models." (PMID 36429101, 2022). "In vivo alterations of the tumor immune environment involved fewer protumorigenic tumor-associated macrophages (TAMs) and MDSCs due to the suppression of IL-4, IL-13, and CXCL1 expression, and elevated infiltration by antitumor CTLs and NK cells attracted by elevated CXCL9 and CXCL10 levels." (PMID 35499071, 2022). "Moreover, tumor tissues with a high T cell ratio within and close to the tumor nests in relation to the total stroma produced higher levels of CXCL9, CXCL10 and CXCL11, signifying the importance of the CXCR3-axis in T cell localization within the tumor microenvironment." (PMID 35954489, 2022). "Additionally, IFN-γ production by Th1 cells induces secretion of CXCL9 and CXCL10 by tumor-associated macrophages (TAM) and cancer-associated fibroblasts (CAF) as well as tumor cells present in the TME that promote tumor-effector T cell infiltration in melanoma patients." (PMID 35008422, 2022). "The already-inflamed baseline state of Brca2−/− tumours (Cxcl10high, more T cells) and the reduced expression of PD-1 both help to explain why similar expression levels of Cxcl9 as in the Brca2WT tumours did not cause a significant survival benefit in the Brca2−/− tumours." (PMID 35314795, 2022). "Moreover, the CXCL9, 10, or 11–CXCR3 ligand/receptor pair has also been reported to be downregulated in the metastatic and therapy-resistant tumor, which suggested the upregulation of CXCL9, 10, and 11 might be potential therapy targets for recurrent tumors." (PMID 36561315, 2022).
tumor (continued). "However, anti-PD-L1 treatment acted synergistically with Cxcl9 overexpression and significantly prolonged time to onset of ascites (median 51 vs. 45 days; P = 0.003) and overall survival (median 57 vs. 52 days; P = 0.007) in the Cxcl9+ tumour group." (PMID 35314795, 2022). "Moreover, in a Phase II trial conducted by Lampert and colleagues, testing the combination of the PARP inhibitor olaparib and the anti-PD-L1 antibody durvalumab, sequentially obtained tumour biopsies revealed an upregulation of CXCL9 and an induction of TILs 14 days after onset of therapy." (PMID 35314795, 2022). "However, Karin suggested that CXCL10 and CXCL9 may differ from other chemokines in their ability to inhibit tumor growth and enhance anti-tumor immunity." (PMID 36479091, 2022). "Therefore, we speculated that one of the mechanisms for the overexpression of CXCL9 in nonCD8+ PBMCs was induced by either tumor- or activated dendritic cells-secreted type I interferons." (PMID 34680466, 2021). "Although this mechanism contributes to the suppression of tumor progression, it may be offset by the inhibition of the angiostatic cytokines CXCL9, CXCL10, and CXCL11; this can promote, in addition to tumor neovascularization, tumor growth or metastasis formation." (PMID 34442627, 2021). "Pathogenic microorganisms and tumor cells can be eliminated by M1 macrophages by acute proinflammatory response, immune activation reaction, and cytophagy through the release of proinflammatory factors, such as NO, IL-1β, IL-6, TNF-α, and chemokines such as CCL2, CCL3, CCL5, CXCL9, and CXCL10." (PMID 34506209, 2021). "Similarly, NK cells can be chemoattracted by CXCL9 and specifically recognize IL-2 on tumor cells." (PMID 34603454, 2021). "Along with epigenetic silencing of tumor-suppressor genes, in different types of cancer cells, EZH2 upregulation is linked with the transcriptional repression of genes that confer immunogenicity (e.g., MHC I and II) and support the recruitment of effector T cells (e.g., CXCL9 and CXCL10)." (PMID 33922336, 2021). "These may include therapies that directly supply T cell chemotactic chemokines, such as CXCL-9, -10, and -11, into tumor or promote their production from tumor cells, or deplete Tregs, or therapies that block IFNγ or its induced immunoregulatory effects through blockade of IDO or PD-1." (PMID 34943886, 2021). "Moreover, CXCL9 can exert a tumor suppressive function in tumors." (PMID 34163353, 2021). "The combination treatment caused increased secretion of CCL2, CCL21, CXCL1, CXCL2, CXCL5, CXCL9 and CXCL16, whereas the levels of CCL11, CCL17, CCL19, CCL22, CCL25, CCL27 and CX3CL1, which are associated with protumourigenic effects, were decreased in the tumours." (PMID 33014356, 2020). "The observed synergy in tumor rejection extended to different tumor models, was accompanied by increased numbers of activated T cells expressing high levels of Gzma, Gzmb, Perforin, Cxcr3, and increased intratumoural levels of Cxcl9 and Cxcl10 compared to wild-type mice." (PMID 32641748, 2020). "However, CXCL9 contributes to not only tumor inhibition but also tumor promotion." (PMID 32963527, 2020). "However, we did not see any apparent impact of Mcpt6 deficiency on CD8 expression in the tumors, suggesting that any impact of CXCL9 on tumor progression may be explained by effects beyond its influence on CD8+ T‐cell recruitment." (PMID 31894627, 2020). "However, some studies also indicated that these chemokines might play tumorigenic roles by promoting tumor metastasis and proliferation; thus, the specific roles of CXCL9 and CXCL10 in PC remain unclear." (PMID 33363572, 2020). "In addition, low CXCL9 or low PD-L1 was associated with shorter RFS in patients with higher tumor cell proliferation and in patients without instillation therapy." (PMID 33003392, 2020).
tumor (continued). "Therefore, targeting PTPN2 may not only enhance the antigen‐specific activation and function of CAR T cells, but also limit “on‐target off‐tumour” toxicities by driving the homing of CXCR3‐expressing CAR T cells to CXCL9/10/11‐expressing tumours." (PMID 31803974, 2020). "Interestingly, we found an increased percentage of MHCII+CD11c+ DC expressing CXCL9 in the tumor mass upon administration of anti–CTLA-4 antibody and Tα1, suggesting that Tα1 can indeed modify the chemokine profile at the tumor site likely by regulating the expression program of DCs." (PMID 32817121, 2020). "CXCL9 treatment could significantly increase the STAT3 activity in the PAAD tumour of mice." (PMID 31913856, 2020). "While clear borderline between the tumour and normal tissues could be observed in mice of control group, dim boundary in the tissue of CXCL9-treated mice was found, suggesting more tumour invasion and infiltration after CXCL9 treatment." (PMID 31913856, 2020). "This study highlights how the loss of mature miRNAs in TAMs during tumor progression leads to increased classically activated TAMs, improved CD8 response, and decreased CD8 suppression, which was associated with higher expression of CXCL10, CD86, and CXCL9 in the tumors." (PMID 31710308, 2019). "Thus, depending on the tumor cell type, CXCL9 can have either an adverse or a beneficial effect." (PMID 31216755, 2019). "However, DOC didn’t influence the levels of CXCL10 and CXCL9 in tumor cells." (PMID 30744691, 2019). "Indeed, Th1-secreted IFN-γ was shown to trigger a cytotoxic activity of tumor-associated macrophages (TAMs) and also induces CXCL9/MIG and CXCL10/IP-10 secretion by macrophages, which may affect the tumor progression by angiogenesis inhibition." (PMID 29780381, 2018). "Interestingly, the expression of CXCL9 is restricted to macrophages present in the perivascular area, indicating heterogeneity among macrophages within the tumor, and suggesting this cell type as the most important player for the recruitment of CTL in the perivascular space." (PMID 30319638, 2018). "This marked sensitivity of the immune C26 tumor microenvironment to corticosterone was also reflected by the correlation between anti-IL-6-induced decreased plasma levels of the hormone and increased mRNA levels of Cxcl9, Cxcl10, and Cxcl11 in food-restricted pre-cachectic C26-bearing mice." (PMID 27829137, 2016). "Moreover, in RCC, pervious studies found the expression of CXCL9, CXCL10 and CXCL11 increased in tumor compared to normal kidney tissues, suggesting the association with TILs and favorable prognosis, and the promotion of tumor specific immunity in systemic high-dose interleukin-2 (IL-2) therapy." (PMID 26910919, 2016). "Moreover, CXCL9 can promote the migration and invasion of tumor cells." (PMID 27738495, 2016). "Furthermore tumor-expressed CXCL9 was shown to be crucial for immune control of murine cutaneous fibrosarcomas while CXCL11 secretion by genetically modified mouse T cell lymphoma cells (EL4) led to increased infiltration of CD8+CXCR3+ T cells and subsequent tumor rejection." (PMID 23874342, 2013). "The connectivity between IL-12 and CXCL9 seen in the networks from mildly symptomatic patients is also observed in the context of cancer therapy, in which administration of IL-12 increases the expression of CXCL9 in peripheral blood mononuclear cells as a response against the tumour." (PMID 23433077, 2013). "This could imply a separate, non-T-cell-mediated, anti-tumor effect associated with CXCL9, or suggest that the time points analyzed were not optimal for analysis of lymphocyte infiltration." (PMID 21884585, 2011). "(c) Signaling molecules also play a role, as the density of tumor-infiltrating T cells is negatively associated with expression of VEGF, B7-H1/PD-L1 and endothelin B receptor by tumors and positively associated with expression of the chemokines CXCL9, CCL21, CCL22, CCL2 and CCL5." (PMID 19641607, 2009).
tumor (continued). "Within the tumor microenvironment (TME), the C-X-C motif chemokine ligand 9 (CXCL9) plays a pivotal yet paradoxical role, functioning as both an anti-tumor effector and a tumor-promoting factor depending on its cellular origin." (PMID 41766875, 2026). "By defining the role of VISTA in controlling Cxcl9:Spp1 ratio and modulating CD8+ T cell dynamics, this study positions VISTA inhibition as a promising strategy to reshape the TME and potentiate anti-tumor immunity in PDAC." (PMID 41776161, 2026). "CXCL9 and CXCL10 can be produced by antigen-presenting cells, such as dendritic cells or macrophages, as well as by tumor cells." (PMID 41399390, 2026). "JUN, FOS, STAT3, JUND and NR2F1 were up-regulated in clusters C2 and C3, leading to tumor progression and immune evasion by influencing target genes HSPA1A, CXCL9 and PDGFR." (PMID 42074110, 2026). "For example, CXCL9 and CXCL10 recruit effector T cells into the tumor via CXCR319, 20, promoting anti-tumor responses, while CCL2 recruits MDSCs through CCR2, thereby inhibiting immune responses." (PMID 41399390, 2026). "Our results suggest that OCDMs inhibit CXCL9:SPP1 macrophage polarity and promote the transformation of macrophages into pro‐tumor macrophages." (PMID 40056029, 2025). "Activation of this pathway results in the release of chemokines such as CCL5, CXCL9, and CXCL10, which recruit immune cells—including CD8+ T lymphocytes, macrophages, and dendritic cells—into the tumour microenvironment." (PMID 40596709, 2025). "Chemokines such as C-C motif chemokine ligand 5 (CCL5), C-C motif chemokine ligand 11 (CCL11), C-X-C motif chemokine ligand 9 (CXCL9), and C-X-C motif chemokine ligand 10 (CXCL10) are believed to be primary mediators of eosinophil-driven tumor necrosis." (PMID 40761780, 2025). "Since the CXCR3-CXCL9 axis plays a critical role in tumor infiltration and reinvigoration of CD8+ T cells in response to PD-1 blockade, we next examined the role of CXCL9 and CXCR3 in mediating the anti-tumor effects of DB using the B16-OVA tumor model." (PMID 40867314, 2025). "Specifically, IL-11 activates STAT3 phosphorylation, which inhibits IFNγ-induced STAT1 phosphorylation, thereby downregulating MHC-I and CXCL9 expression in tumor cells and impairing CD8+ T cell infiltration—promoting immune evasion and tumor growth in CRC." (PMID 41359051, 2025). "Analysis of spatial transcriptomics using deep learning techniques has revealed that clustered arrangements of CXCL9+ cDC1s and stem‐like TCF1+ CD8+ T cells at the tumor–stroma interface correlate with tumor regression." (PMID 40667699, 2025). "In a murine tumor model, the administration of this engineered bacterial strain changed the tumor microenvironment by elevating IFN‐γ and CXCL9 levels, increasing T‐cell infiltration, and enhancing immune activation in the murine tumor model." (PMID 40415505, 2025). "Analysis of cDC1 heterogeneity in samples from cancer patients also reported the existence of CXCL9+ and CCR7+ cDC1s in human tumours." (PMID 40745918, 2025). "The CXCL9/10/11–CXCR3 axis guides immune cell chemotaxis toward tumor sites through concentration gradients and antagonizes VEGF to suppress tumor angiogenesis." (PMID 40574854, 2025). "Despite this, considering known functions of CXCL9 and CXCL10, maintenance of high levels of these chemokines in tumor cells or TAMs lead to a greater abundance of effector T-cells associated with diseased tissues." (PMID 40176808, 2025). "The combination of intratumoral injection of CXCL9/10-DC with immune checkpoint blockade (ICB) therapy effectively overcame therapeutic resistance and established systemic,tumor-specific immunity." (PMID 40064803, 2025). "Proinflammatory chemokines typically produced by DCs to promote the recruitment of T cells, such as CCL5, CXCL9, and CXCL10, were increased in the tumor microenvironment of mice treated with the combination." (PMID 40578365, 2025).
tumor (continued). "This suppression reduces the intratumoral levels of chemokines such as CXCL9 and CXCL10, thereby impairing Teff recruitment and infiltration into the tumor site 54-55." (PMID 40303336, 2025). "By contrast, M1 macrophages, though less well classified and capable of subtype interconversion, dominate early tumor stages, releasing TNF-α, CXCL9, CXCL10, iNOS, and ROS to induce inflammation and eliminate tumor cells." (PMID 40948759, 2025). "Serum HMGB1 levels reflect tumor cell lysis and ICD-driven DC activation, whereas CXCL9/CXCL10 gradients predict Batf3-dependent CD103+ DC migration and T-cell priming." (PMID 40989107, 2025). "Specifically, tumor-bearing mice were treated with DB together with control IgG, or neutralizing antibodies for CXCR3 (αCXCR3, 140 μg/mouse) every 4 days or CXCL9 (αCXCL9, 200 μg/mouse) every 3 days, starting 6 days after B16-OVA cell inoculation." (PMID 40867314, 2025). "For instance, CXCR3, a receptor for chemokines CXCL9, CXCL10, and CXCL11, is more highly expressed in tumor tissues than in normal tissues." (PMID 39940842, 2025). "MTAP-deficient cancer cells showed impaired induction of key chemokines, CXCL9, CXCL10, and CXCL11, particularly in response to immune cell interaction, thereby contributing to the development of an immunosuppressive “cold” tumor microenvironment." (PMID 41246302, 2025). "We also observed higher mRNA expression levels of the CXCR3 ligand genes CXCL9 and CXCL10 in TLS-positive as compared to TLS-negative tumors, suggesting the recruitment of CD8 + T cells into tumor mass." (PMID 40319321, 2025). "The effects of the CXCL9/CXCL10/CXCL11-CXCR3 axis can vary, even within the same organ, depending on the distribution of CXCR3 subtypes in tumor cells." (PMID 40362215, 2025). "Similar to what we observed in murine tumours, we identified a higher proportion of CCR7+ cDC1s located within 10 μm of the TCF1+ mask compared with CXCL9+ cDC1s." (PMID 40745918, 2025). "In a mouse LLC tumor model, intravenous injection of such NP significantly reduced tumor volume and increased CXCL9, CXCL10, and CXCL11 protein levels in tumor tissues." (PMID 40124344, 2025). "These spatial and prognostic patterns align with previous reports implicating CXCL9 as a marker of immunoactive macrophages and SPP1 as a regulator of tumor progression and immune evasion." (PMID 40725473, 2025). "The chemokine CXCL9 attracts cells that express the CXCR3 receptor, such as NK cells, to the tumor site." (PMID 40211394, 2025). "Consistently, mRNA expression analysis of subcutaneous tumor tissues derived from CT26 cell injections showed analogous upregulation of PD-L1, CCL5, CXCL9, and CXCL10." (PMID 40959109, 2025). "Key members of the chemokine family, CXCL9, CXCL10, and CXCL11, bind to their shared receptor CXCR3 to regulate immune cell differentiation, directional migration, and tumor infiltration." (PMID 40574854, 2025). "Activated tumor-infiltrating eosinophils produce high levels of chemokines, such as CCL5, CXCL9, and CXCL10, which attract co-metastatic CD8 + T cells to the tumor, leading to tumor rejection and prolonged survival." (PMID 39141277, 2025). "We found that CXCL9+ cells produced CCL18, a strong lymphocyte attractant, suggesting that CXCL9+ cells attract lymphocytes to the tumour vicinity." (PMID 40670667, 2025). "CXCL9 expression by cDC1s has been suggested to be important for CD8+ T cells recruitment to tumours, including in regions rich in cDC1s at the tumour borders." (PMID 40745918, 2025). "The homing of activated tumour antigen‐specific CD8+ T cells to the tumour microenvironment (TME) is mediated by chemokines CXCL9 and CXCL10 that are produced, among other cells, by tumour‐resident cDC1." (PMID 40878038, 2025). "Given that CXCL9 and CXCL13 expression appears to be induced by anti-PD-L1-CRT and that these cells localize to the vicinity of the tumour, we next sought to identify these cell types through the expression of genes that identify cell types." (PMID 40670667, 2025).